AXL (AXL receptor tyrosine kinase)
Diseases named in the same sentence as AXL in open-access papers (continued):
Sharing a sentence is not in itself a finding about the gene and the disease.
lung cancer (continued). "Moreover, forced expression of AXL in EGFR mutant lung cancer cell lines that are sensitive to erlotinib induced erlotinib resistance through the kinase activity of AXL." (PMID 22970367, 2012). "In addition, PTBP1 can also play a pro‐lung cancer role by regulating the stability of mRNA of downstream target genes, and PTBP1 can promote the progression of lung cancer through the binding of RRM1 to AXL mRNA, resulting in its unstable regulation of AXL expression." (PMID 40579921, 2025). "In addition, AXL overexpression is found to enhance DTC survival in EGFR‐mutant lung cancer." (PMID 37638338, 2023). "Notably, AXL–induced EMT transition is a common occurrence in many TKI–resistant lung cancers, including those resistant to Osimertinib, a third–generation EGFR–TKI that may induce AXL." (PMID 37834326, 2023). "In addition, it has been demonstrated that AXL activation is involved in the generation and maintenance of DTCs in lung cancer treated with axitinib, and that the application of AXL inhibitors in combination with targeted drugs is effective in preventing DTCs both in vitro and in vitro." (PMID 37483492, 2023). "Interestingly, downregulation of the receptor tyrosine kinase AXL has been suggested to enhance the response of HNSCC cells (584 and 1386-LN), as well as breast and lung cancer cells, to olaparib and which was linked with reduced levels of RAD51 foci and decreased HR efficiency." (PMID 36052247, 2022). "Therefore, we searched for other factors associated with the Hippo signaling pathway that could affect YAP‐dependent gene responses in lung cancer cells with high AXL expression." (PMID 33207077, 2021). "Thus, EGCG inhibits the stemness and tumourigenicity of human lung cancer cells by inhibiting AXL." (PMID 32051483, 2020). "AXL/GAS6 are known to be a pivotal signaling axis involved in EMT, which could conceivably be the underlying factor in leading to tumor progression and adverse prognosis in lung cancer BM." (PMID 28551766, 2017). "However, there are insufficient data on how MET- or AXL-mediated resistance to EGFR-TKI in lung cancer could be overcome by inhibiting HSP90." (PMID 25780909, 2015). "In addition to AXL overexpression, MET overexpression and the expression of its ligand, HGF have both been described as in vitro and in vivo mechanisms of resistance to EGFR TKI therapy in EGFR-mutated lung cancers." (PMID 25337673, 2014). "The cell lines exhibiting the strongest co-expression of ADAM9, TNFRSF12A, and AXL were 2 ovarian cancer lines (OVCAR_8 and SK_OV_3), lung cancer line HOP_92, and several renal cancer lines, suggesting that these cell lines may be particularly active in degrading extracellular matrix." (PMID 22570691, 2012). "AXL, a member of the Tyro3-AXL-Mer (TAM) receptor tyrosine kinase (RTK) family, has emerged as a promising therapeutic target for lung cancer frequently overexpressed in metastatic tumors, AXL is strongly associated with resistance and poor survival outcomes." (PMID 40302940, 2025). "Other highly significant features include sHER2/sEGFR2/sErbB2, AXL, TGFa, and FGF2, demonstrating strong predictive power in lung cancer classification." (PMID 40217526, 2025). "While MIG6 and AXL are both correlated with EMT and EGFR signaling pathways, how AXL, MIG6 and EGFR interplay in lung cancer remains elusive." (PMID 37834326, 2023). "For example, chemotherapy-induced AXL expression was reported in AML, lung cancer, prostate cancer, ovarian cancer, and endometrial cancer as conferring therapy resistance." (PMID 36835239, 2023). "To assess AXL and MIG6 (ERRFI1) mRNA expression in NSCLC patients, we analyzed the Lee lung dataset from Oncomine and the lung cancer cell lines from the CCLE (Cancer Cell Line Encyclopedia)." (PMID 37834326, 2023). "Increased expression of AXL and CDCP1 was observed in refractory tumor samples from patients with lung cancer treated with osimertinib." (PMID 35643725, 2022).
lung cancer (continued). "We design AXL-directed CAR-T cells and show that their anti-tumour activity can be improved in combination with MWA in several preclinical lung cancer models." (PMID 36261437, 2022). "Two of the top upregulated genes—AXL and SPOCK1 for H1975 and H23, respectively—were of interest as they are known to be involved in signaling pathways important to lung cancer development and resistance to targeted therapy." (PMID 33712563, 2021). "AXL expression was positively correlated with PD-L1 and CXC chemokine receptor 6 (CXCR6) expression in lung cancer, especially in mtEGFR-expressing NSCLC." (PMID 34830794, 2021). "AXL-RTK is a key mediator of developing treatment resistance in various cancers including prostate, breast, ovarian, colorectal and lung cancers." (PMID 34140003, 2021). "KRT19, SPARC, SPOCK, LINC00707 (lung cancer promoting lincRNA), FOSL1 and AXL (identified as downstream targets of TS as they appeared in both signatures) were qPCR validated in both cell lines." (PMID 33024270, 2021). "Particularly, doxorubicin treatment in mesenchymal‐type lung cancer cells also activated TGFβ‐SMAD4 signaling, which in turn primed YAP/TAZ activity toward AXL expression." (PMID 33207077, 2021). "As expected, EMT and YAP signatures were strongly enriched in high‐AXL patients, thereby confirming the YAP‐dependent expression of AXL in mesenchymal‐type lung cancer cells." (PMID 33207077, 2021). "LC‐MS/MS proteomic analysis reveals that CAFs that overexpress hMENAΔv6 secrete the AXL ligand GAS6, favoring the invasiveness of AXL‐expressing pancreatic ductal adenocarcinoma (PDAC) and non‐small cell lung cancer (NSCLC) cells." (PMID 32909687, 2020). "In the present study, we focused on AXL expression and EMT activation due to their important biological roles in lung cancer." (PMID 31703465, 2019). "It has been reported that AXL is closely relevant to EGFR signaling pathway and mediates the resistance to EGFR inhibition in lung cancer and GBM." (PMID 29843637, 2018). "The activity prediction algorithm was then implemented for the regulatory networks of six important lung cancer oncogenes (FAK, PXN, MET, RON (MST1R), EPHA2, AXL)." (PMID 29731983, 2018). "To elucidate the biological significance of AXL in lung cancer metastases, especially in NSCLC with brain metastases, we tested the expression of AXL and its ligand GAS6 in the selected 98 lung cancer specimens by immunohistochemical staining." (PMID 28551766, 2017). "Of importance, preventing cleavage of AXL seems to promote cell survival and resistance to erlotinib, a prescribed TKI drug of epidermal growth factor receptor, in non–small-cell lung cancer (NSCLC) cells." (PMID 28034848, 2017). "Overexpression of AXL has been observed in nearly 60% of NSCLC cell lines, and it is also found highly expressed among primary lung cancers." (PMID 28551766, 2017). "AXL has been nominated as a potent epithelial–mesenchymal transition (EMT) inducer, and a potential molecular target for lung cancer therapy." (PMID 28551766, 2017). "The Axl receptor tyrosine kinase (RTK) has been shown to modulate acquired resistance to EGFR-targeted therapies in both breast and lung cancers." (PMID 27775700, 2016). "Cell models used included Hep3B, C3A, HepG2 and Huh7, several of which showed an upregulation of erlotinib-resistance genes, AXL, HGF, FGFR1 and ERBB3 in comparison to an erlotinib-sensitive lung cancer line." (PMID 24551227, 2014). "Interestingly, AXL has been found to influence acquired resistance to EGFR-targeted therapies in both breast and lung cancers." (PMID 39924521, 2025). "Furthermore, research findings revealing the immunomodulatory functions of AXL have provided strong support for the combinational treatment of AXL inhibition and ICI treatment in primary tumor models of breast and lung cancers." (PMID 38310091, 2024).
lung cancer (continued). "Other studies reported a correlation between high AXL expression and lower MHC-I levels in lung carcinoma cell clones, though AXL inhibition did not upregulate MHC-I." (PMID 39367387, 2024). "Also, natural products (NP) activate apoptotic pathways in lung cancer cell including p‐JNK, Akt/mTOR, PI3/ AKT\ and Bax, Bcl2, but suppressed AXL phosphorylation." (PMID 37697969, 2023). "However, the expressions of other receptors (AXL, BSG, KREMEN1, and TFRC) were significantly down-regulated in lung cancer patients." (PMID 38034398, 2023). "Here, we show that PI4K2A stabilizes AXL and coordinates exocytic and endocytic trafficking of SPP1 and its receptors, respectively, to activate a protumorigenic autocrine loop in mesenchymal lung cancer cells." (PMID 36757799, 2023). "Many of the Gas6/AXL studies have concentrated on lung cancer, but not much is known about other different environments where Gas6 and AXL are affected as those observed during PE." (PMID 35741013, 2022). "In fact, lung cancer has become an interesting model to elucidate the mechanism of action of NT157 since, in this model, signaling mediated by IGF1R-IRS1/2, STAT3, and AXL has already been reported as relevant to the development, progression, and therapeutic response of this type of cancer." (PMID 36224313, 2022). "Interestingly, AXL inhibition was shown to concomitantly reduce autophagy and modulate ICD in a lung cancer cell model." (PMID 34745989, 2021). "At present, the potential effects of MET and/or AXL targeting have been reported in renal cell carcinoma, lung cancer, and triple‐negative breast cancer." (PMID 34766112, 2020). "Moreover, the co-expression relationship between AXL and GAS6 was further confirmed by IHC assays in serial sections of lung cancer metastasis tissues." (PMID 28551766, 2017). "Highly phosphorylated AXL is frequently found in human NSCLC cell lines and lung cancer tissues, but AXL is not expressed in normal lung tissues." (PMID 29259259, 2017). "In lung cancer, AXL was identified as a potential target for overcoming EGFR inhibitor resistance and combination of an AXL specific inhibitor (SGI-7079) with Erlotinib reversed Erlotinib resistance in a xenograft model of mesenchymal non-small cell lung cancer." (PMID 25193853, 2014). "The requirement for co-development and co-approval of CDx in order to get TKIs approved against these RTK (ROS1, RET, NTRK1, AXL, PDGFR-α) rearrangement lung cancer represents the daunting challenge to successfully translate decades of basic science research into benefit of cancer patients." (PMID 24744988, 2014). "For example, EGFR-TKI resistance could be caused by MET amplification, HGF-triggered MET activation, Gas6-triggered AXL activation, and HER2 amplification in EGFR mutant lung cancer." (PMID 24952482, 2014). "It has been demonstrated that targeting AXL with SLC-391, alone or in combination with chemotherapy or immune checkpoint blockade, results in tumour growth inhibition in multiple solid tumour and haematological tumour models, including lung cancer, colon cancer, CML, and AML." (PMID 41471387, 2025). "AXL could affect cytotoxic immune response against tumors by reducing the expression of intercellular adhesion molecule 1 (ICAM1) and UL16 binding protein 1 (ULBP1) in mesenchymal human lung cancer cells." (PMID 37328828, 2023). "According to a recent study, AXL is stimulated by osimertinib after the termination of a negative feedback loop into SPRY4 in EGFR‐mutant lung cancer cells, resulting in the expression of HER3 and EGFR to maintain cell survival and promote osimertinib tolerance." (PMID 37638338, 2023). "To test whether AXL promotes SARS-CoV-2 infection in primary lung epithelium, we established human primary lung epithelial spheroids using epithelial cells isolated from para-carcinoma lung tissues obtained from lung cancer patients." (PMID 33420426, 2021).
lung cancer (continued). "Moreover, AXL and the other TAM receptors (TYRO3 and MERTK) have been reported as key mediator of chemoresistance in neuroblastoma through induction of EMT and in lung cancer through the regulation of mitogen-activated protein kinase (MAPK) and FAS signaling pathways." (PMID 34745951, 2021). "Upregulation of AXL and its major ligand GAS6, has been reported in a wide variety of cancer cell lines as well as in cancer specimens from patients with breast cancer, acute leukemia, colorectal cancer, lung cancer, melanoma, ovarian cancer, or prostate cancer, among others." (PMID 27829217, 2016). "Co-activation of MET, AXL, ERBB2, and EPHA2, and co-activation of DDR1 with EGFR, DDR2, HCK, PDGFRA, and FGR is evidence that simultaneous activation of multiple tyrosine kinases may be common in lung cancer." (PMID 23300999, 2013). "Even though we could not show significant post-transcriptional modification of AXL mRNA in our study, this mechanism must be further explored since there is evidence for negative feedback regulation of RTK-AXL by mircoRNAs in response to chemotherapy in lung cancer cells." (PMID 35055167, 2022). "This is consistent with prior reports that YAP depletion or inhibition has no impact on AXL mRNA level in MDA-MB-231 cells and in lung cancer cell lines at the protein level." (PMID 38565949, 2024). "AXL hyperactivation and evidence for EMT were previously reported in multiple in vitro and in vivo EGFR-mutant lung cancer models with acquired resistance to erlotinib independent of the EGFR T790M alteration and MET activation." (PMID 31815659, 2019). "Because various oncoproteins depend on HSP90 for maturation and stability, we investigated the effects of AUY922, a newly developed non-geldanamycin class HSP90 inhibitor, in lung cancer cells with MET- and AXL-mediated resistance." (PMID 25780909, 2015).
breast carcinoma (131 papers, 2007 to 2026). "Analysis of human breast cancer tissue further confirmed that low AXL expression is associated with a higher presence of NK cells in the tumor." (PMID 41009462, 2025). "The result showed that high AXL expression is associated with poorer distant-metastasis-free survival (DMFS) in both breast cancer (p = 0.036) and TNBC (p = 0.043)." (PMID 41009462, 2025). "AXL expression is upregulated in human breast cancer epithelial cells, which results in the loss of epithelial-type shape and the acquisition of markers associated with mesenchymal tissue." (PMID 38391974, 2024). "AXL is frequently overexpressed in solid tumors, such as pancreatic and breast cancers, and is associated with worse prognosis and resistance to antitumor treatments (radiotherapy, chemotherapy, and targeted therapy)." (PMID 38132919, 2023). "AXL expression is associated with increased risk of metastasis and poor survival in a variety of solid cancers, including breast cancer, non‐small‐cell lung adenocarcinoma, ovarian cancer, clear cell renal carcinoma, and pancreatic cancer." (PMID 36409270, 2023). "AXL expression is associated with metastasis and poor prognosis in a variety of tumor types including breast cancer." (PMID 35813203, 2022). "AXL-mediated oncogenic functions have been linked to disease aggressiveness and therapy resistance in breast cancer and PDAC." (PMID 35993361, 2022). "Nevertheless, it is now well established that AXL expression is linked to increased risk of metastasis and poor survival in a variety of solid cancers including breast cancer, non-small cell lung carcinoma, ovarian cancer, and clear cell renal carcinoma." (PMID 35158733, 2022). "In this study, we sought to define the role of AXL in VM formation and to understand the mechanism underlying VM formation in breast cancer cells." (PMID 33374832, 2020). "Despite the elevated levels of AXL seen in breast malignancies, less than 2.5% of breast cancers exhibit any alteration in AXL (mutation, rearrangement, etc.), and amplifications specifically are also exceedingly rare (less than 2%)." (PMID 32148495, 2020). "Consistently, Slug is associated with aggressive forms of breast cancer, thereby highlighting AXL’s key role in tumor progression." (PMID 33182542, 2020). "AXL has attracted attention as a driver of therapeutic resistance, i.e., high AXL expression is closely associated with the acquisition of drug resistance in lung and breast cancer cells." (PMID 32051483, 2020). "In breast cancer, AXL was associated with doxorubicin-resistance through AKT/GSK-3β/β-catenin activation." (PMID 31694201, 2019). "These factors are co-located with AXL-expressing cells in situ in normal and breast cancer tissues, and associated with resistance to paclitaxel." (PMID 29719832, 2018). "Overexpression of AXL has been demonstrated to cause drug resistance in lung and breast cancer cells." (PMID 28034848, 2017). "Up-regulation of AXL is associated with poor survival of breast cancer, lung adenocarcinoma, and acute myeloid leukemia." (PMID 27172793, 2016). "Systemic inhibition of AXL signaling in the tumor microenvironment with the treatment of an AXL monoclonal antibody inhibited inflammatory cytokine secretion from tumor associated macrophages in a breast cancer model." (PMID 27834845, 2016). "Then, we investigated the biological mechanisms underlying the cross-talk between AXL-expressing breast cancer cells and TAMs, and its impact on tumor progression and anticancer drug resistance." (PMID 28721387, 2016). "Overexpression of the RTK AXL has been implicated in the tumorigenesis of several tumor entities such as pancreatic, liver, and breast cancer, glioma, and primary HNSCC." (PMID 28025482, 2016). "High levels of activated AXL have been linked to increased chemoresistance in lung and breast cancers, esophageal carcinoma, and acute myeloid leukemia." (PMID 26573603, 2015).